VDAC1 (voltage dependent anion channel 1)
Diseases named in the same sentence as VDAC1 in open-access papers (continued):
Sharing a sentence is not in itself a finding about the gene and the disease.
diabetes (20 papers, 2009 to 2025). "Our previous studies demonstrated that VDAC1 is upregulated and participates in diabetes-related dysfunction in the leptin-deficient db/db mouse model of T2D." (PMID 32093016, 2020). "Additionally, two proteins, silent information regulator 1 (Sirt1) and Voltage-dependent anion-selective channel protein 1 (VDAC1), implicated in regulating diabetes, were identified." (PMID 38510357, 2024). "In the current work, we have linked the dysregulation and mistargeting of the diabetes executer protein VDAC1 to the suppression of GPR56, thereby linking this adhesion GPCR to β-cell mitochondrial dysfunction with impaired ATP accumulation and compromised insulin secretion." (PMID 36979492, 2023). "Thus, it cannot be rigorously stated that an increase in the level of VDAC1 (and/or other proteins) can directly underlie the pathological changes in the cell observed in diabetes/hyperglycemia." (PMID 37507997, 2023). "Likewise, in diabetes, coronary endothelia cells display higher rates of apoptosis due to mitochondrial Ca2+ overload, which was linked to enhanced VDAC1 protein levels." (PMID 33477936, 2021). "Binds to the VDAC1 target, improving conditions such as diabetes, COVID-19, cancer, neurodegenerative diseases, and aging." (PMID 40538812, 2025). "This underscores the potential benefits of using the VDAC1-based peptide as a treatment for diabetes." (PMID 39334905, 2024). "In particular, pharmacological or genetic inactivation of the VDAC1 protein of the outer membrane mitigates mitochondrial dysfunction and oxidative stress in diabetes mellitus in in vitro and in vivo models." (PMID 39334925, 2024). "The development of diabetes mellitus is accompanied by an increase in VDAC1 expression in a number of tissues and organs." (PMID 37507997, 2023). "Another study showed that in diabetes, heart failure develops due to coronary microvascular rarefaction induced by apoptosis in coronary endothelia through increased VDAC1 expression." (PMID 33477936, 2021). "report on the role of the ATP-conducting mitochondrial outer membrane voltage-dependent anion channel-1 (VDAC1) in β cell glucotoxicity preceding diabetes." (PMID 30293774, 2019). "The role of VDAC1 in the development of hyperglycemia was also examined in the db/db mouse, a commonly used diabetes model." (PMID 30293774, 2019). "Protein expression of mitochondrial specific integral membrane proteins such as the mitochondrial import receptor subunit TOM70 and voltage dependent anion channel (VDAC-1) were unaffected by diabetes or exercise." (PMID 23936397, 2013). "A number of studies have shown that the development of diabetes mellitus is accompanied by an increase in VDAC1 expression, which may be one of the factors in the development of this pathology." (PMID 37507997, 2023). "Indeed, co-immunoprecipitation assay results showed that enhancement of SIRT3 expression by HKL decreased the interaction between IP3R, GRP75 and VDAC1 in diabetes model mice." (PMID 37481555, 2023). "Moreover, considering that VDAC1 is highly expressed in states of glucotoxicity, such as in pre-diabetes patients, verapamil could prevent the development and progression of diabetes, as also shown in previous clinical studies." (PMID 38089047, 2023). "In this study, we examined the effects of the VDAC1-derived peptide, R-Tf-D-LP4, on several parameters of a NAFLD model on a diabetic background (STZ/HFD-32), with the focus on diabetes." (PMID 32093016, 2020). "Direct inhibition of VDAC1 in human T2D β cells restores GSIS and prevents development of diabetes in db/db mice." (PMID 30293774, 2019).
Parkinson disease (20 papers, 2015 to 2025). A progressive degenerative disorder of the central nervous system characterized by loss of dopamine producing neurons in the substantia nigra and the presence of Lewy bodies in the substantia nigra and locus coeruleus. "In fact, an association between VDAC1 and mitophagy has been previously reported primarily in Parkinson's disease." (PMID 26472185, 2015). "Abolishing VDAC1 monoubiquitinylation by introducing a K247R mutation in VDAC1 induced a Parkinson disease phenotype in fruitflies was associated with excessive apoptosis and could be relieved by MCU knock-out." (PMID 33477936, 2021). "Another group of Chu and colleagues linked VDAC1 to cellular injury in Parkinson's disease." (PMID 26106253, 2015). "In Parkinson’s disease, α-synuclein directly interacts with mitochondria, blocks VDAC1, and impairs metabolite fluxes leading, consequently, to an energetic crisis able to compromise cell viability." (PMID 34884639, 2021). "There is broad evidence showing the participation of VDAC-1 in Parkinson’s disease via its interaction with α-synuclein mediating its transport via the pore-regulating Ca2+-homeostasis, altogether providing evidence for the involvement of VDAC-1 in neurodegenerative diseases." (PMID 38474278, 2024). "Furthermore, monoubiquitination of VDAC1 is important in the regulation of apoptosis and lack of monoubiquitination of VDAC1 phenocopies parkinsonism, including locomotion defects and loss of dopaminergic neurons, suggesting that regulation of apoptosis plays a role in disease pathogenesis." (PMID 33800736, 2021). "In a cellular model of Parkinson’s disease, the dopaminergic cell line SH-SY5Y was exposed to the mitochondrial complex-1 inhibitor rotenone leading to increased VDAC-1 levels, while in post-mortal brain tissue, VDAC-1 levels are clearly reduced." (PMID 38474278, 2024).
neuroblastoma (19 papers, 2008 to 2025). Neuroblastoma (NB) is the most common solid, extracranial childhood tumor. "In support of a tight correlation between Aβ levels and VDAC1 expression, it is interesting to underline that soluble Aβ oligomers were able to induce VDAC1 upregulation in a human neuroblastoma cell line." (PMID 35887070, 2022). "For example, in AD post-mortem brains, in neuroblastoma cells and in an AD mouse model, a direct association was demonstrated between VDAC1, specifically its N-terminal region, and hyper-phosphorylated Tau but also with amyloid beta (Aβ), both in its monomeric and oligomeric forms." (PMID 34884639, 2021). "While the VDAC1-N-terminal peptide shows protective effects against Aβ-mediated human neuroblastoma cell apoptosis, VDAC1 facilitates Aβ-mediated cell toxicity, demonstrating mitochondrial dysfunction and apoptosis induction." (PMID 38674050, 2024). "VDAC1 regulates ER-mitochondria Ca2+ signaling, and Aβ is capable to upregulate VDAC1 in human neuroblastoma cell line." (PMID 34440085, 2021). "The pl-VDAC-1 contributes to apoptosis as demonstrated in neuronal cells such as the human neuroblastoma cell line SK-N-MC, in the mouse hippocampal cell line HT22, and in primary differentiated hippocampal neurons which were stimulated with the protein kinase inhibitor staurosporine." (PMID 40649921, 2025). "Interestingly, amyloid-β (Aβ) soluble oligomers were able to induce upregulation of VDAC1 in a human neuroblastoma cell line, further supporting a correlation between Aβ levels and VDAC1 expression." (PMID 34884639, 2021). "Interestingly, RNA-based silencing of hAβPP, Tau, and VDAC-1 genes in human neuroblastoma cells results in improved mitochondrial function." (PMID 29691440, 2018). "In addition, the use of VDAC1-based peptides (residues 10–30) suggests that VDAC1 is part of a system controlling cell proliferation in neuroblastoma cells via its interaction with glucose-regulated protein 78 (GRP78)." (PMID 28824871, 2017). "Given that VDAC1 is mainly involved in the trafficking of charged molecules in and out of mitochondria, a general reduction of cell viability and mitochondrial respiration was detected in neuroblastoma cells and primary cortical neurons exposed to Aβ oligomers." (PMID 40223243, 2025). "Similar results were observed using the human neuroblastoma cell line NMB as the administration of dopamine induced apoptosis, along with a reduction on the mRNA level for VDAC-1, VDAC-2, and VDAC-3." (PMID 40649921, 2025).
cervical carcinoma (18 papers, 2010 to 2025). A carcinoma arising from either the exocervical squamous epithelium or the endocervical glandular epithelium. "This study revealed that patients with cervical cancer whose cancer tissues exhibited positive VDAC1 immunoreactivity had a higher risk of recurrence and poor overall survival." (PMID 26716410, 2016). "This study aims to explore the association between expression of hOGG1, VDAC1, HK-2 and cervical carcinoma." (PMID 20846459, 2010). "And the expression of hOGG1, VDAC1, HK-2 were detected by the method of IHC for exploring the association between them and cervical cancer." (PMID 20846459, 2010). "Therefore, VDAC1 was hypothesized to be associated with the development and progression of cervical cancer." (PMID 26716410, 2016). "Current studies also show that Grp75 and VDAC1 regulate the release of Ca2+ in cervical cancer and ovarian cancer." (PMID 40243820, 2025). "It has been reported that highly expressed VDAC1 exacerbated the clinical progression of cervical cancer patients." (PMID 35958281, 2022). "VDAC1 has also been identified with poor outcomes in other types of malignant tumors, such as pancreatic cancer, hepatocellular carcinoma, and cervical cancer." (PMID 35729567, 2022). "We also analyzed the relationships of different clinicopathologic variables with KMT2A/VDAC1 expression in cervical cancer patients." (PMID 32436862, 2020). "The in vivo results from a cervical cancer xenograft mouse model also validated that KMT2A knockdown suppressed tumor growth by inhibiting VDAC1, whereas KMT2A overexpression promoted cervical cancer growth." (PMID 32436862, 2020). "We found that the expression of VDAC1 in cervical cancer was higher than the cervix normal tissue in one of six databases." (PMID 32436862, 2020). "At the same time, we analyzed the expression level of VDAC1 and its clinical significance in cervical cancer using Oncomine database." (PMID 32436862, 2020). "We found that the expression of VDAC1 in cervical cancer was higher than the cervix normal tissue in one of six databases, and the expression of VDAC1 was upregulated in Biewenga Cervix database." (PMID 32436862, 2020). "In this study, we investigated the role of KMT2A on cervical cancer cell growth, cell migration and cell apoptosis via VDAC1signal and found that VDAC1 was in downstream of KMT2A in the process of cervical cancer cell growth." (PMID 32436862, 2020). "Nevertheless, the specific mechanism by which KMT2A targeted VDAC1, thereby regulating cell growth in cervical cancer cells remains to be further explored." (PMID 32436862, 2020). "We next analyzed the expression level of VDAC1 and its clinical significance in cervical cancer using Oncomine database." (PMID 32436862, 2020). "miR-320a promotes mitophagy by down-regulating VDAC1 expression during serum starvation in cervical cancer cells." (PMID 29112159, 2017). "Voltage-dependent anion channel 1 (VDAC1) was found to be highly oxidized in HPV-positive cervical cancer cells." (PMID 27419626, 2016). "The clinical implication was shown that cervical cancer tissues with positive VDAC1 immunoreactivity exhibited deep stromal invasion (>10 mm in depth) and large tumor size (> 4 cm in diameter)." (PMID 26716410, 2016). "After the nm23-H1 gene was silenced, the expression of VDAC1 was elevated in the mRNA and protein levels in SiHa and CaSki cervical cancer cells in this study." (PMID 26716410, 2016). "Mitochondrial membrane potential was decreased and reactive oxygen species generation was increased in the VDAC1 gene-silenced cervical cancer cells." (PMID 26716410, 2016). "Cervical cancer patients with positive VDAC1 immunoreactivity displayed higher recurrence and poorer overall survival than those with negative VDAC1." (PMID 26716410, 2016). "Compared to normal counterparts, our findings showed that the VDAC1 immunoreactivity was significantly stronger in cervical cancer tissues." (PMID 26716410, 2016).
cervical carcinoma (continued). "The cell motility was found to be significantly reduced with a wound healing assay after the VDAC1 gene had been silenced in SiHa cervical cancer cells with lentiviruses carrying shVDAC1 #128 and #564." (PMID 26716410, 2016). "We then investigated the relationship between VDAC1 immunoreactivity of cancer tissues and clinicopathological characteristics of cervical cancer patients." (PMID 26716410, 2016). "To detect the expression of the candidate proteins in HPV16-positive cervical cancer tissues, we used IHC staining to assess the expression of VDAC1, VDAC2, VDAC3 and HPV16 E7." (PMID 27419626, 2016). "After silencing VDAC1 in SiHa and CaSki cervical cancer cells, the cell growth was significantly inhibited." (PMID 26716410, 2016). "The JC-1 monomer ratio was increased in VDAC1 gene-silenced SiHa or CaSki cervical cancer cells compared to their control counterparts." (PMID 26716410, 2016). "We next investigated the influence of VDAC1 gene silencing on the growth and metastatic potential of cervical cancer cells." (PMID 26716410, 2016). "SiHa and CaSki cervical cancer cells in which the VDAC1 gene had been silenced were established, and reduced mRNA levels and protein contents of VDAC1 were confirmed in these cancer cells." (PMID 26716410, 2016). "We found that the cytotoxicity of cisplatin was significantly enhanced in the SiHa and CaSki cervical cancer cells in which the VDAC1 gene had been silenced." (PMID 26716410, 2016). "The expression of voltage-dependent anion channel 1 (VDAC1) was increased in nm23-H1 gene silenced SiHa or CaSki cervical cancer cells." (PMID 26716410, 2016). "VDAC1 expression correlated significantly with the invasion of cervical cancer, the grade of cervical intraepithelial neoplasia (CIN) and the expression of HPV16 E7 in CIN." (PMID 27419626, 2016). "We found that the cell growth was reduced after VDAC1 gene silencing in SiHa and CaSki cervical cancer cells." (PMID 26716410, 2016). "We then investigated the role of VDAC1 in cell growth and the metastatic potential of uterine cervical cancer cells." (PMID 26716410, 2016). "Because HPV16 E7 promotes the progression of cervical cancer, we assessed the expression of VDAC1 and HPV16 E7 in precancerous (CIN) and normal tissues using IHC staining." (PMID 27419626, 2016). "Taken together, our results demonstrated that serum starvation induced CREB1 expression to activate miR-320a expression, which then suppressed VDAC1 expression to promote mitophagy, enhancing the survival of cervical cancer cells." (PMID 26472185, 2015). "To explore the unsettled puzzle, develop more significant biomarker of cervical cancer and cervical precancerous lesions, we analyzed the expression of hOGG1, VDAC1 and HK-2 in cervical biopsy tissue." (PMID 20846459, 2010). "Cervical cancer patients who displayed high VDAC1 immunoreactivity have been shown to experience higher rates of recurrence and poorer overall survival compared to those with lower VDAC1 levels." (PMID 39456237, 2024). "Furthermore, VDAC1 has been shown to prevent the progression of HPV-induced cervical cancer and DHX9–lncRNA–MDM2 interactions regulate tumor cell invasion and the angiogenesis of CESC." (PMID 36900213, 2023). "In addition to cervical carcinoma, VDAC1 expression was investigated only for lung, head and neck, and esophageal squamous cell carcinoma." (PMID 37046443, 2023). "Therefore, larger sample sizes are required to reveal the role of VDAC1 in the prognosis of cervical cancer patients." (PMID 35958281, 2022). "SOX21-AS1 facilitates the progression of cervical cancer by targeting the miR-7/VDAC1 pathway." (PMID 34511042, 2021). "Considering that VADC1 can mediate the release of apoptotic proteins and interacts with anti-apoptotic proteins and plays a key role in the process of mitochondria-mediated apoptosis, in this study we are interested in and focused on the KMT2A/VDAC1 signaling axis in cervical cancer." (PMID 32436862, 2020).
cervical carcinoma (continued). "Our results showed that KMT2A regulated cervical cancer growth by targeting VDAC1 signaling." (PMID 32436862, 2020). "As the grade of cervical cancer deepened, the expression of VDAC1 decreased." (PMID 32436862, 2020). "Because VDAC1 can bind with pro-apoptotic or anti-apoptotic proteins, it may stimulate or inhibit the apoptosis, growth and survival of cervical cancer cells respectively." (PMID 26716410, 2016). "We first evaluated VDAC1 expression in cervical cancer cells (SiHa, S12, CaSki, C33A and HeLa)." (PMID 27419626, 2016). "Therefore, in cervical cancer cells in which the VDAC1 gene had been silenced, it prevented the interaction of hexokinase and VDAC1, subsequently reduced glycolysis and energy production and then increased the generation of ROS and inhibited cell growth." (PMID 26716410, 2016). "VDAC1 expression correlated significantly with the invasion of clinical cervical cancer." (PMID 27419626, 2016). "To determine whether downregulation of VDAC1 would induce apoptosis in cervical cell lines, we used CRISPR-VDAC1 to block the expression of endogenous VDAC1 in human cervical cancer S12 and SiHa cells." (PMID 27419626, 2016). "Among these isoforms, VDAC1 has been shown to be the most abundant in HeLa cervical cancer cells." (PMID 26716410, 2016). "Therefore, we investigated the clinical implication of VDAC1 in cervical cancer and found that the immunoreactivity was significantly stronger in cervical cancer tissues than that in normal tissues (p<0.001, median: 1.5 vs. 0.5, n=150 vs. 29)." (PMID 26716410, 2016). "Furthermore, when HeLa cervical cancer cells stably expressing shRNA directed against VDAC1 were injected into nude mice, the development of a solid tumor was inhibited." (PMID 26472185, 2015). "Furthermore, we added reagents that could dissociate the binding of hexokinase and VDAC1, including methyl jasmonate and clotrimazole, to cisplatin in the SiHa and CaSki cervical cancer cells to detect their effects on cell viability." (PMID 26716410, 2016). "In vitro, the cervical cancer cell line (HeLa) highly expresses VDAC, and VDAC1 silencing has been proved to inhibit cancer cell proliferation." (PMID 35958281, 2022). "To determine the possible regulation of KMT2A on VDAC1, we analyzed the effects of KMT2A and VDAC1 on cell growth, migration and apoptosis in cervical cancer cells." (PMID 32436862, 2020). "To identify the clinical significance of KMT2A/VDAC1 signaling axis, we detected their expression in cervical intraepithelial neoplasia (CIN) and cervical cancer tissue samples." (PMID 32436862, 2020). "Moreover, analyses of Biewenga cervix database and clinical samples showed that both KMT2A and VDAC1 were upregulated in cervix squamous cell carcinoma compared with cervix uteri tissues, and their expression was negatively correlated with the differentiation grade of cervical cancer." (PMID 32436862, 2020). "As VDAC1 expression was induced by HPV16 E7 expression, it may be that, like HPV16 E7, VDAC1 acts as an oncoprotein in cervical cancer." (PMID 27419626, 2016). "In summary, our study has demonstrated that KMT2A regulates cervical cancer cell growth via targeting VDAC1 signaling, indicating that the KMT2A/VADC1 signaling axis may be a new mechanism of cervical tumorigenesis and a potential therapeutic target for cervical cancer treatment." (PMID 32436862, 2020). "In summary, the present study indicated that VDAC1 may interact with HPV16 E7 to promote the malignant progression of HPV-related disease, especially in the precancerous stage, and that the expression of VDAC1 correlated with the invasion of cervical cancer." (PMID 27419626, 2016).